RNU6-856P (RNA, U6 small nuclear 856, pseudogene)
Gene: Small nuclear RNA gene on chromosome 3 (52,551,846 to 52,551,943, reverse strand). Ensembl gene ENSG00000252768.
Homologues: Orthologues: chimpanzee U6 (100% identical), macaque U6 (95% identical). Paralogues in human: RNU6-1158P (85% identical), RNU6-38P (85% identical), RNU6-842P (85% identical), RNU6-1042P (84% identical), RNU6-1117P (84% identical), RNU6-242P (84% identical), RNU6-41P (84% identical), RNU6-468P (84% identical), RNU6-476P (84% identical), RNU6-799P (84% identical), RNU6-1145P (83% identical), RNU6-166P (83% identical), and 1288 more.